RN7SL719P (RNA, 7SL, cytoplasmic 719, pseudogene)
Gene: Miscellaneous RNA gene on chromosome 15 (28,703,554 to 28,703,790, reverse strand). Ensembl gene ENSG00000274632.
Homologues: Orthologues: chimpanzee Metazoa_SRP (99% identical), pig Metazoa_SRP (59% identical). Paralogues in human: RN7SL469P (99% identical), RN7SL673P (99% identical), RN7SL628P (99% identical), RN7SL82P (99% identical), RN7SL495P (99% identical), RN7SL185P (97% identical), RN7SL196P (97% identical), RN7SL286P (97% identical), RN7SL539P (97% identical), RN7SL796P (97% identical), Metazoa_SRP (92% identical), RN7SL106P (92% identical), and 708 more.